PINK1 (PTEN induced kinase 1)
Diseases named in the same sentence as PINK1 in open-access papers (continued):
Sharing a sentence is not in itself a finding about the gene and the disease.
neuroblastoma (65 papers, 2007 to 2026). Neuroblastoma (NB) is the most common solid, extracranial childhood tumor. "We first established that the loss of PINK1 or Parkin protein in human neuroblastoma SH-SY5Y cells induces an increase in the mitochondrial oxidative state while the cytosolic redox state remains unaltered." (PMID 29529199, 2018). "Similar to the previous findings in Pink1−/− mice, an upregulation of RSAD2 and a downregulation of HEBP1 were observed in the starving PINK1-deficient neuroblastoma cells." (PMID 28768533, 2017). "PINK1 KD in neuroblastoma cells is associated with a significant reduction in the TMRM signal by 43% compared to controls (n > 120 cells in >2 clones, p < 0.0001)." (PMID 19285945, 2009). "Similarly, the siRNA-mediated knockdown of PINK1 in SH-SY5Y neuroblastoma cells caused decreased mtDNA levels and reduced mitochondrial ATP synthesis, establishing the role of PINK1 in mitochondrial biogenesis." (PMID 39594485, 2024). "However, a previous study showed that Rosi prevented the loss of mitochondrial PINK1 in neuroblastoma, which implied decreased mitophagy." (PMID 35028008, 2022). "Moreover, SH-SY5Y neuroblastoma cells exposed to conditioned medium of PINK1-deficient mixed glia show increased death that can be prevented with an inhibitor of iNOS." (PMID 29321620, 2018). "Mutation in PARK6 gene (PINK1) has been observed in neuroblastoma, so raising the hypothesis that alteration of mitophagy may have a causal role in certain tumors." (PMID 28512624, 2017). "Three independent experiments in SH-SY5Y human neuroblastoma (above) and murine embryonal fibroblast cells (below) documented the expression of key inflammatory factors in untreated versus drug-treated cells, comparing control with PINK1-deficiency." (PMID 28768533, 2017). "It has been shown that downregulation of ATG7 can compensate the loss of mitochondria in PTEN-induced kinase 1 (PINK1) deficient dopaminergic human neuroblastoma cells, likely supporting the potential role of ATG7 in PINK1 mutation-related familial Parkinson’s disease." (PMID 26404030, 2015). "PINK1 overexpression in the neuroblastoma cell line SHSY5Y could rescue cell death caused by neurotoxins." (PMID 24324558, 2013). "Furthermore, the PD-related protein PINK1 was also identified as an interaction partner of Miro1 in human neuroblastoma cells and primary fly neurons for the trafficking of mitochondria, and the loss of PINK1 led to aberrations in mitochondrial morphology and dynamics." (PMID 33041957, 2020). "Miro1 has direct interactions with certain proteins encoded by PD-linked genes such as PTEN-induced kinase 1 (PINK1), PARKIN and Leucine-rich repeat kinase 2 (LRRK2) (as witnessed in human neuroblastoma cells and D. melanogaster primary neurons)." (PMID 37150812, 2023). "Numerous studies using a human neuroblastoma cell line report that decreased PINK1 content led to increased mitochondrial fragmentation, and cell death." (PMID 36526679, 2022). "In this study we used SH-SY5Y neuroblastoma cells, a model for cancer and PD, to demonstrate that PINK1 impairs the pro-apoptotic cleavage of Beclin1, tipping the balance towards autophagy after STS treatment." (PMID 35203326, 2022). "CERKL alleviated neuronal damage through activating mitophagy in a SIRT1/PINK1/Parkin-dependent pathway in human neuroblastoma cells." (PMID 36507335, 2022). "In SH-SY5Y neuroblastoma cells, the depletion of PINK1, ATP13A2, and/or GBA resulted in cell death, as demonstrated by elevated LDH levels, decreased cell viability, and increased levels of the cleaved form of caspase-3 or Gasdermin D." (PMID 34035300, 2021). "For example, experiments using SH-SY5Y human neuroblastoma cells that were stable knockdown for PINK1 showed an enhancement of the mitophagy process by increasing oxidative stress." (PMID 34356302, 2021).
neuroblastoma (continued). "In Tau and APP-expressing neuroblastoma cells, overexpression of P301L mutant Tau or mutant APPswe impairs the translocation of mitochondrial Parkin, PINK1, LC3-II/I, and other mitophagy-related proteins." (PMID 34867159, 2021). "Lack of PINK1 increases glia-mediated primary neuron apoptosis and nitric oxide (NO)-dependent neuroblastoma cell death, suggesting that PINK1 in glial cells promotes a neuronal protective effect." (PMID 33168089, 2020). "PINK1 and PRKN (encoding PARKIN) get transcriptionally induced in human neuroblastoma cells after serum deprivation or nutrient starvation, linking dietary restriction to mitophagy." (PMID 33023155, 2020). "The PINK1 (PTEN-induced putative kinase 1) gene contains putative ARE regulatory elements in its promoter region and Nrf2 has been demonstrated to active PINK1 transcription in human neuroblastoma cell lines." (PMID 33099215, 2020). "Conversely, overexpression of PINK1 increases AKT phosphorylation in human SH-SY5Y neuroblastoma cells." (PMID 31884871, 2020). "We used differentiated human dopaminergic neuroblastoma cell lines with stable PINK1 or DJ‐1 knockdown to study live motility of mitochondria in neurites." (PMID 30133157, 2018). "α-Syn and PINK1 were expressed individually or else co-expressed for 24h with plasmids or lentivirus (LV) in SK-N-SH neuroblastoma cells or primary cortical neurons; the overexpression of these proteins was confirmed by immunocytochemistry." (PMID 29416594, 2018). "The present data from Pink1−/− mouse brain, human neuroblastoma cells, and patient fibroblasts serve as additional corroboration in vivo, providing a spatio-temporal framework and identifying crucial molecular mediators." (PMID 28768533, 2017). "In neuroblastoma cells, the poly(I:C) triggered inductions were significantly blunted by PINK1 knockdown for RSAD2, DDX58, IFIT3, and IFIT1." (PMID 28768533, 2017). "Many studies especially in neuroblastoma cells show that mitochondrial membrane depolarization stabilizes Pink1 on the outer mitochondrial membrane leading to the recruitment of Parkin, cessation of movement and the rapid induction of autophagy." (PMID 24885281, 2014). "Here, we characterize in human dopaminergic SH-SY5Y neuroblastoma cells the dynamics of Miro1 ubiquitination by the PINK1/Parkin mitochondrial quality control system." (PMID 24671417, 2014). "In the cytoplasm, PINK1 forms a complex with parkin and DJ-1, which promotes the ubiquitination and degradation of parkin substrates in neuroblastoma cells." (PMID 23244239, 2012). "In cervical cancer and neuroblastoma cells, parkin and PINK1 have also been shown to play a critical role in the selective macroautophagy of mitochondria." (PMID 21264221, 2011). "We found that Parkin-induced mitophagy is also dependent on PINK1 expression in the M17 human neuroblastoma cell line." (PMID 20126261, 2010). "Re-expression of WT, but not kinase mutant PINK1, restored the basal NADH redox level in PINK1 KD neuroblastoma cells to values equivalent to the controls (59.7% ± 5.1%)." (PMID 19285945, 2009). "To confirm the role of NOX in the production of ROS, we performed siRNA of gp91phox (the major subunit of NOX2 expressed in brain) in human PINK1 KD neuroblastoma cells (n = 2 clones)." (PMID 19285945, 2009). "Application of 5 mM pyruvate to PINK1 KD neuroblastoma cells resulted in an increase in basal respiration to control values (from 0.41 ± 0.033 nmol/O2/min/106 cells to 0.81 ± 0.09 nmol/O2/min/106 cells; n = 4 experiments; p < 0.001)." (PMID 19285945, 2009). "Calcium-induced depolarization in PINK1 KD neuroblastoma cells was prevented by preincubation of cells with 0.5 μM CsA (n = 48; data not shown)." (PMID 19285945, 2009). "To address the function of PINK1 in living cells, we generated stable dopaminergic neuroblastoma lines that express wild-type PINK1, a recessive mutant, G309D and an artificial variant lacking kinase activity." (PMID 19492085, 2009).
neuroblastoma (continued). "One possible explanation for the apparent difference between our results, which are consistent with some other results in human neuroblastoma cell lines, and those in Drosophila models is that the effects of PINK1 on mitochondrial morphology are indirect." (PMID 19492085, 2009). "In human PINK1 KD neurons, the rate of glucose uptake was 54.1% ± 5.1% of control (n = 58 for control; n = 63 for KD) In PINK1 KD neuroblastoma cells, the rate of glucose uptake was 63.8% ± 5.4% of control cells (n = 112 for control; n = 94 for KD; p < 0.001)." (PMID 19285945, 2009). "Application of 100 μM ATP to neuroblastoma cells induced a [Ca2+]c signal in both control (n = 61) and PINK1 KD cells (n = 56)." (PMID 19285945, 2009). "Stable re-expression of wild-type (WT)-PINK1 or the kinase-dead mutant K219M-PINK1 was achieved in PINK1 knockdown (KD) neuroblastoma cells and confirmed by RT-PCR." (PMID 19285945, 2009). "Using RNAi, we created stable PINK1 knockdown in human dopaminergic neurons differentiated from foetal ventral mesencephalon stem cells, as well as in an immortalised human neuroblastoma cell line." (PMID 18560593, 2008). "We produced stable knockdown models of PINK1 using small interfering RNAs in two complementary cell lines–human neuroblastoma SHSY5Y and a novel human NSC line capable of high levels of DAergic differentiation." (PMID 18560593, 2008). "We profiled, using Northern blot, a range of neuroblastoma cell lines to look for divergent expression of the PINK1 related transcripts (with a view towards future cell studies)." (PMID 17362513, 2007). "Furthermore, enhanced stability of SIRT1 by overexpression of Ceramide Kinase-Like Protein (CERKL) promoted the production of PINK1 and Parkin in human neuroblastoma cells of OGD/R." (PMID 36507335, 2022). "Previous research has shown that cytosolic PINK1 fragments enhanced Parkin-mediated ubiquitination and degradation of Parkin substrates in neuroblastoma cells and human brain lysates, and bioinformatic analysis presented the potential involvement of Parkin in the ubiquitination of tau." (PMID 35059394, 2021). "A similar induction of Pink1 and Prkn, accompanied by increased autophago-lysosomal degradation of mitochondria, was also reported in human neuroblastoma cells upon deprivation from fetal calf serum, which contains transferrin as the key supplier of iron during cell culture." (PMID 33023155, 2020). "Moreover, we show that conditioned medium from PINK1−/− mixed glia confers increased NO-dependent toxicity to SH-SY5Y neuroblastoma cells, compared to conditioned medium from WT mixed glia." (PMID 29321620, 2018). "Furthermore, the interaction of PINK1 with the MAPK pathway has already been demonstrated experimentally in neuroblastoma cells, astrocytes, HeLa, and HepG2 liver cells." (PMID 28768533, 2017). "Thus, Miro levels upon mitochondrial damage, in dopaminergic neuroblastoma cells and in human fibroblasts, are controlled by the PINK1/Parkin pathway." (PMID 24671417, 2014). "To determine whether mutant PINK1 affects mitochondrial function, we generated Flag-tagged wild type, L347P, E417G or Del 245 PINK1-adenovirus to infect human neuroblastoma SH-SY5Y cells with high efficiency." (PMID 19242547, 2009). "In addition, FAD2+ level was more oxidized in PINK1 KD neuroblastoma cells (PINK1 KD, 49.7% ± 4.3%, compared to control, 37.5% ± 2.9%, p < 0.05)." (PMID 19285945, 2009). "Additionally, in neuroblastoma cell lines, neuronal cells expressing mutant A53T α-Syn or W437X Pink1 showed significant increases in mitochondrial size, which could contribute to alterations in neuronal profiles." (PMID 40075409, 2025). "Furthermore, in the PTEN-induced putative kinase 1 (PINK1), a genetically mutated model of PD in mice, pre-treatment with curcumin improves cell viability, improves mitochondrial membrane potential, and reduces apoptosis in SH-SY5Y neuroblastoma cells." (PMID 34681908, 2021).
neuroblastoma (continued). "This is seen in neuroblastoma cells where the dual inhibition of KAT5 and KAT8 inhibits the initial steps of PTEN-induced kinase 1 (PINK1)-dependent mitophagy." (PMID 38790268, 2024). "In the same context, the overexpression of PINK1 stabilized mitochondrial networking and function in SH-SY5Y neuroblastoma cells." (PMID 34356302, 2021). "In HEK293 cells or SH‐SY5Y neuroblastoma cells that were pretreated with the mitochondrial CHCHD4/GFER system inhibitor MitoBloCK‐6, CCCP‐ or FCCP‐induced PINK1 accumulation was remarkably inhibited." (PMID 32779864, 2020). "In human neuroblastoma SH-SY5Y cells, UA treatment increased the levels of a set of mitophagy-related proteins such as parkin, full-length PINK1 (F-PINK1), p-ULK1 (Ser 555), BECN1, AMBRA1, and Bcl2L13, leading to mitophagy induction." (PMID 31824296, 2019). "We further confirmed the interaction of endogenous PINK1 with LETM1 from human post-mortem brain and human SH-SY5Y neuroblastoma cells." (PMID 29123128, 2017). "In neuroblastoma cells treated with toxins such as staurosporine and MG132, PINK1 overexpression suppresses toxin-induced damage." (PMID 24324558, 2013). "In a human neuroblastoma cell line, the administration of its receptor ligand GDNF compensates morphological and bioenergetic deficits of PINK1-deficient cells without affecting mitophagy." (PMID 28768533, 2017). "In NOX2-siRNA PINK1 KD cells, the basal ROS production was significantly reduced compared to PINK1 KD cells treated with scrambled siRNA (from 315.6% ± 25.7% to 126.7% ± 9.4% of control, n = 96 control neuroblastoma cells; n = 92 for PINK1 KD; n = 127 for NOX2-siRNA PINK1 KD)." (PMID 19285945, 2009). "Additionally, treating neuroblastoma cells with MG149, a KAT8 inhibitor, impairs global H4K16 acetylation and autophagy regulator PTEN-Induced Kinase 1 (PINK1) expression of neuroblastoma cells further inhibiting autophagy receptor p62 recruitment, resulting in autophagy." (PMID 40508066, 2025). "We find Miro ubiquitination in dopaminergic neuroblastoma cells is independent of Miro1 phosphorylation at Ser-156 but is dependent on the recently identified Ser-65 residue within Parkin that is phosphorylated by PINK1." (PMID 24671417, 2014). "Since NIX, similar to AMBRA1, induces alternative mitophagy (PINK1- and PARKIN-free), it would be of the highest interest to test in this context whether NIX-mediated mitophagy can rescue cell death following 6-OHDA or rotenone treatments in human neuroblastoma cell lines." (PMID 29755319, 2018). "Re-expression of WT PINK1, but not K219M-PINK1, rescued the TMRM signal in neuroblastoma cells (data not shown)." (PMID 19285945, 2009).
Alzheimer disease (56 papers, 2007 to 2026). A progressive, neurodegenerative disease characterized by loss of function and death of nerve cells in several areas of the brain leading to loss of cognitive function such as memory and language. "The current knowledge has displayed the molecular mechanisms underlying mitophagy dysregulation in Alzheimer’s disease, especially in relation to the PINK1–Parkin-mediated mitophagy." (PMID 36982968, 2023). "We recognize that in some cases, such as with PD-associated mutations in PINK1 and Parkin, the association is direct, while in others, such as with Alzheimer’s disease (AD), the association is only indirect." (PMID 36339819, 2022). "It is therefore conceivable that PINK1 and Parkin are also linked to the pathogenesis of other neurological diseases including Alzheimer's disease." (PMID 23533695, 2013). "Indeed, there are links for the UPRmt in protecting dopaminergic neurons in C. elegans defective in PINK1/Parkin mitophagy, while the UPRmt has also been linked to Alzheimer’s disease." (PMID 37738349, 2023). "In a different context, the involvement of mtDNA signaling in pathogenesis of Alzheimer’s disease (AD) is also currently under discussion, as several reports of mitochondrial dysfunction and also the dysfunction of Pink1/Parkin, excessive ROS production are reported in association with AD." (PMID 35223833, 2022). "Moreover, according to a recent study, decreased expression of PINK1 is associated with increased Aβ accumulation, mitochondrial dysfunction, and impairments in learning and memory in a mouse model of Alzheimer disease." (PMID 31711042, 2019). "Previous studies have demonstrated Rg1's ability to modulate mitophagy, such as by activating the PINK1/Parkin pathway to ameliorate Alzheimer's disease or by providing protection against nutritional stress in H9c2 cells via the AMPK/PINK1 signalling pathway." (PMID 40458031, 2026). "This preservation occurs through BDNF-mediated activation of the AMPK/PINK1/Parkin pathway in Alzheimer’s disease models." (PMID 40035032, 2025). "In another study, PINK1 levels were notably elevated in the cerebrospinal fluid and serum samples of patients with multiple sclerosis or Alzheimer’s disease." (PMID 40979207, 2025). "For example, the PINK1/Parkin-mediated inhibition of mitochondria has been found in Alzheimer’s disease mice and β-amyloid-induced cellular models of SH-SY5Y cells, along with the exacerbation of neuroinflammation and cellular focal death." (PMID 40497971, 2025). "Recently, cholesterol levels have been tied to PINK1 biology and to defective mitophagy in Alzheimer’s disease." (PMID 37627263, 2023). "PINK1/Parkin pathway alterations have also been found in many neurodegenerative diseases such as Parkinson's disease (PD), Alzheimer's disease (AD), and Huntington's disease (HD)." (PMID 35126814, 2022). "UA improved associative memory and neuronal survival through the induction of PINK1 expression in neurons of an Alzheimer’s disease mouse model." (PMID 35546176, 2022). "The use of Drosophila models of various neurodegenerative diseases already revealed valuable findings, such as essential insights into the pathology of Alzheimer’s disease (AD) or the interaction of PINK1 and Parkin in PD." (PMID 36589738, 2022). "The downregulated expression of Parkin and abnormal PINK1 accumulation were reported in the brains of patients with Alzheimer’s disease." (PMID 33003463, 2020). "Defective mitophagy and PINK1/PARKIN signalling are present in neurodegenerative diseases including Alzheimer’s disease (AD), Parkinson’s disease (PD) and glaucoma." (PMID 33168089, 2020). "Mutations in PTEN (phosphatase and tensin homolog deleted on chromosome 10) and PINK1 (PTEN-induced putative kinase 1) have been linked to neurodegenerative disease processes affecting ALS, Parkinson's and Alzheimer's Diseases." (PMID 24406377, 2014).